MALT1 (MALT1 paracaspase)
Diseases named in the same sentence as MALT1 in open-access papers (continued):
Sharing a sentence is not in itself a finding about the gene and the disease.
Autoimmunity (continued). "Moreover, MALT1 also regulates the activation of DC cells, NK cells and mast cells, indicating the possibility that MALT1 activity in some of these cells may also regulate inflammatory T and B cell responses associated with autoimmunity in Malt1-PD mice." (PMID 31474984, 2019). "We report that both lines develop similar disease symptoms and autoimmunity, indicating that MALT1 proteolytic activity suppresses autoimmunity in a T cell-intrinsic manner." (PMID 31474984, 2019). "This, as well as the signal fine-tuning by an enzymatic activity, makes MALT1 protease activity a very attractive therapeutic target in humans for the treatment of autoimmunity and some cancers." (PMID 31474984, 2019). "In this case, MALT1 inhibition was shown to protect against EAE by blunting T-cell mediated autoimmunity." (PMID 29367251, 2018). "Nevertheless, because of its MALT1 inhibitory effects, a repurposing of mepazine for the treatment of autoimmunity and ABC-DLBCL has been proposed." (PMID 30513612, 2018). "The observed autoimmunity is likely the result of reduced development of natural Treg (nTreg) cells in MALT1-PI mice." (PMID 30214442, 2018). "MALT1 has recently been proposed to be a promising therapeutic target in autoimmunity and B cell lymphomas and a current approach is to target the proteolytic functions of MALT1." (PMID 29371921, 2017). "We demonstrate significant protective activities of mepazine when administered either early (before the onset of acute disease) or late (at the peak of disease), illustrating that MALT1 is not only an attractive drug target in cancer but also in autoimmunity." (PMID 25043939, 2014). "Furthermore, reconstitution of the full-body Malt1-PD mice with T cell-specific expression of wild-type human MALT1 eliminated all signs of autoimmunity." (PMID 31474984, 2019). "The reduced CTLA-4 expression could thus be an important factor regulating autoimmunity in the Malt1-PDT mice." (PMID 31474984, 2019). "The reduced Treg numbers are likely caused by the absence of MALT1 function during development, since no spontaneous autoimmunity develops in adult mice treated with small molecule MALT1 inhibitors for up to 17 days." (PMID 30214442, 2018). "Moreover, our results showing first positive and then negative regulation of NF-κB activation by MALT1 indicate that therapeutic intervention with MALT1 inhibitors for autoimmunity or lymphoid neoplasia needs to be considered carefully." (PMID 26525107, 2015). "Indeed, mice expressing an autoprocessing-resistant mutant of MALT1 have a partial Treg deficit that results in enhanced anti-tumor immunity without causing autoimmunity." (PMID 30214442, 2018). "By combining TRAF6 ablation and MALT1 paracaspase inactivation selectively in T cells, we provide genetic evidence that T effector responses and autoimmunity in the absence of TRAF6 relies on MALT1 protease activation." (PMID 36761777, 2023). "In this study the absence of TRAF6 or mutations in MALT1 impairing the interaction with TRAF6, enhanced the T cell activation independent protease activity of MALT1 and caused flagrant autoimmunity in mice." (PMID 35251035, 2022). "Our findings support the view implicated from the animal models, in which autoimmune phenotype is associated with the abolishment of MALT1 protease activity, whereas the development of autoimmunity is not seen in MALT1 knock-out (KO) mice." (PMID 32870913, 2020). "In contrast, complete absence of MALT1 does not lead to autoimmunity, which has been explained by the impaired effector T cell activation due to the absence of MALT1-mediated signaling." (PMID 31632405, 2019). "Importantly, MALT1 protease activity is required to maintain high expression of CTLA-4 on Treg cells and it was shown that even a moderate decrease in CTLA-4 expression can lead to autoimmunity." (PMID 36761777, 2023).
Autoimmunity (continued). "However, information on the therapeutic potential of small compound inhibitors that target MALT1 protease activity in autoimmunity is still lacking." (PMID 25043939, 2014).
B-cell lymphomas (20 papers, 2013 to 2025). "Our current findings underline that MALT1 inhibitors are promising therapeutic agents for B-cell lymphomas that are dependent on chronic BCR signaling." (PMID 36922488, 2023). "Mucosa-associated lymphoid tissue lymphoma translocation gene 1 (MALT1), originally identified in B-cell lymphoma, is a Cys-dependent, Arg-specific protease." (PMID 30619766, 2018). "MALT1 plays a crucial role in the activation of the NFκB pathway, with implications in lymphoid malignancies including B cell lymphomas." (PMID 41294852, 2025). "Suppression of MALT1 protease activity with small molecule inhibitors showed promising efficacies in subtypes of B cell lymphoma and improvement in experimental autoimmune encephalomyelitis model." (PMID 27105502, 2016). "Constitutive MALT1 activity is one characteristic of specific types of B-cell lymphomas, rendering MALT1 as a potential drug target for these malignancies." (PMID 26788853, 2016). "The importance of MALT1 protease activity was shown recently by the dependency of NF-κB-addicted B cell lymphomas on this proteolytic activity." (PMID 25922601, 2015). "Recently, small molecule inhibitors of MALT1 proteolytic activity were identified and shown to have promising anticancer properties in subtypes of B cell lymphoma." (PMID 25043939, 2014). "Analysis of specific genes such as MALT1 should improve the precision of B-cell lymphoma diagnosis." (PMID 34873224, 2021). "Recently, the protease activity of MALT1 has received particular attention as a drug target for the treatment of ABC DLBCL, a particularly aggressive form of human B-cell lymphoma that is dependent on the oncogenic activation of the CARMA1-BCL10-MALT1 pathway and on the protease activity of MALT1." (PMID 23977204, 2013). "The combined detection of lymphocyte clonality and MALT1 translocations using BALF is suitable for screening and diagnosis of B-cell lymphomas." (PMID 34873224, 2021). "In contrast, no MALT1 processing was detectable in the B cell lymphoma cell line BJAB, which is derived from the germinal center B-cell (GCB) subtype of DLBCL and has no steady MALT1 protease activity." (PMID 25105596, 2014).
psoriasis (16 papers, 2011 to 2025). An autoimmune condition characterized by red, well-delineated plaques with silvery scales that are usually on the extensor surfaces and scalp. "Mucosa‐associated lymphoid tissue 1 (MALT1) modulates T helper cell differentiation, pro‐inflammatory cytokine production, and epidermal hyperplasia to participate in the pathology of psoriasis." (PMID 38578002, 2024). "Th17-cell metabolism was studied in an animal model of psoriasis and discovered that the production of the mucosa-associated lymphoid tissue lymphoma translocation protein 1 (MALT1) was dysregulated in Th17 cells." (PMID 36311757, 2022). "As a result, increased blood MALT1 reflected a higher psoriasis risk." (PMID 38578002, 2024). "This hyperactivity is reduced upon MALT1 protease inhibition with mepazine, thus suggesting that MALT1 treatment could benefit patients with CARD14-associated psoriasis." (PMID 30386326, 2018). "Meanwhile, MALT1 regulates T helper (Th) 17 cell and γδ T17 cell differentiation and epidermal hyperplasia to involve in the pathogenesis of psoriasis." (PMID 38578002, 2024). "Pretreatment MALT1 was higher in psoriasis patients who achieved PASI75 (p = .001) and PASI90 (p < .001) at M6 compared to those who did not achieve that." (PMID 38578002, 2024). "Blood MALT1 was increased in psoriasis patients who achieved PASI 75 at M6 compared to those who did not achieve that (p = .001)." (PMID 38578002, 2024). "Although it is known that psoriasis-associated CARD14 mutations induce the association of CARD14 with BCL10 and MALT1, knowledge about the signalling proteins and pathways involved in CARD14 signalling is rather limited." (PMID 39145956, 2024). "In accordance with these previous studies, the present study also figured out that blood MALT1 was increased in psoriasis patients compared with disease controls and healthy controls." (PMID 38578002, 2024). "Blood MALT1 was the highest in psoriasis patients, followed by disease controls, and the lowest in healthy controls (p < .001)." (PMID 38578002, 2024). "Thirdly, from the results of subgroup analyses, blood MALT1 seemed to have a stronger ability to distinguish psoriasis patients with current initiating systemic biologic therapy who achieved PASI 75 and 90 at M6 from those who did not achieve that." (PMID 38578002, 2024). "The post hoc comparison revealed that blood MALT1 was increased in psoriasis patients compared to disease controls and healthy controls (both p < .001); meanwhile, blood MALT1 was also elevated in disease controls versus healthy controls (p = .019)." (PMID 38578002, 2024). "This study aimed to explore the correlation of blood MALT1 with treatment outcomes in psoriasis patients." (PMID 38578002, 2024). "The ROC curve suggested that blood MALT1 had an acceptable ability to discriminate psoriasis patients from disease controls with an area under the curve (AUC) (95% confidence interval [CI]) of 0.735 (0.659–0.810)." (PMID 38578002, 2024). "Secondly, this study discovered that blood MALT1 was elevated in psoriasis patients who achieved PASI 75 and 90 at M6 versus those who did not achieve that." (PMID 38578002, 2024). "The present study aimed to explore the dysregulation of blood MALT1 and its relationship with disease activity and treatment response in psoriasis patients." (PMID 38578002, 2024). "MALT1 was detected in peripheral blood mononuclear cells by reverse transcription‐quantitative polymerase chain reaction in 210 psoriasis patients before starting or converting to a new therapy, 50 disease controls, and 50 healthy controls." (PMID 38578002, 2024). "The activation of NF-κB by gain-of-function psoriasis-associated CARD14 mutants involves CARD14 forming a complex with BCL10 and MALT1." (PMID 39145956, 2024). "MALT1 was increased in psoriasis patients versus disease controls and healthy controls (both p < .001); and positively related to body mass index (p = .019) and PASI score (p < .001) in psoriasis patients." (PMID 38578002, 2024).
psoriasis (continued). "Accordingly, GLS1 or the MALT1 protease activity blockade attenuates Th17 and γδ T17 cell differentiation and epidermal proliferation in a psoriasis-like mouse model." (PMID 37443834, 2023). "This investigation revealed that GLS, or MALT1 inhibitors, previously considered as cancer therapy, can be a potential treatment for psoriasis." (PMID 36311757, 2022). "Given the critical role that MALT1 plays in T cell activation and regulation, there is also emerging interest in the use of MALT1 inhibitors in autoimmune and inflammatory diseases, including psoriasis, colitis, rheumatoid arthritis, and autoimmune encephalitis/multiple sclerosis." (PMID 40231473, 2025). "Blood MALT1 measurement may assist in predicting outcomes in psoriasis patients, especially in those receiving biologics." (PMID 38578002, 2024). "Based on in vitro experiments, we have previously suggested that MALT1 inhibitors might be a good alternative to block CARD14 signalling in psoriasis." (PMID 39145956, 2024). "The findings of this study might provide a reference that the early detection of blood MALT1 was meaningful to predict treatment response in psoriasis patients." (PMID 38578002, 2024). "Psoriasis-associated mutations in CARD14 similarly cluster within the CARD and CC domains and we have recently demonstrated that the highly penetrant CARD14E138A psoriasis-associated mutation induces a conformational change in CARD14 that induces interaction with BCL10 and MALT1." (PMID 39145956, 2024). "Notably, blood MALT1 had a good ability to discriminate psoriasis patients from healthy controls with an AUC (95% CI) of 0.879 (0.831–0.928)." (PMID 38578002, 2024). "Considering psoriasis patients require long‐term treatments, early detection of blood MALT1 before the initiation of treatments, especially systemic biologic therapy, may be helpful in predicting the therapeutic benefits in these patients." (PMID 38578002, 2024). "The potential reasons could be that MALT1 might regulate the c‐Jun pathway to facilitate the hyperproliferation of keratinocytes and the production of chemokines to induce psoriasis." (PMID 38578002, 2024). "Correlation of MALT1 expression with clinical characteristics in psoriasis patients." (PMID 38578002, 2024). "In summary, blood MALT1 may possess the potential to estimate increased disease activity and favorable treatment response, especially to systemic biologic therapy, in psoriasis patients." (PMID 38578002, 2024). "Mechanistically, mucosa-associated lymphoid tissue lymphoma translocation protein 1 (MALT1) protease is constitutively active in CD4 T cells and γδ T cells in psoriasis, and MALT1 can stabilize the binding of c-Jun to the GLS1 promoter region, thereby promoting the expression of GLS1." (PMID 37443834, 2023). "Another possible field of application for MALT1 inhibitors are inflammatory skin diseases such as psoriasis, in which inhibitory effects on keratinocytes and possibly on skin T cells may benefit the patients." (PMID 30214442, 2018). "The present study illustrates its efficiency in a murine model of MS and it will be interesting to study the effect of MALT1 targeting in other inflammatory diseases such as rheumatoid arthritis, psoriasis and inflammatory bowel disease that involve increased T cell receptor signaling." (PMID 25043939, 2014). "However, rare studies report the dysregulation of MALT1 in psoriasis patients." (PMID 38578002, 2024). "A reason behind this might be that MALT1 could regulate immune response, inflammation, and keratinocyte proliferation to facilitate the progression of psoriasis; meanwhile, patients with exacerbated psoriasis might benefit more from treatments." (PMID 38578002, 2024). "The authors also suggested that MALT1 inhibitors promote the reduction of skin inflammation triggered by CARD14 gene mutant variants and therefore may possibly serve as a treatment option in psoriasis." (PMID 34445769, 2021).
psoriasis (continued). "Therefore, topical application of MALT1 inhibitors may be a future treatment option for psoriasis patients." (PMID 30214442, 2018). "In this study, it was found that blood MALT1 was positively correlated with BMI and PASI score in psoriasis patients." (PMID 38578002, 2024). "Blood MALT1 was positively related to BMI (r = .162, p = .019) and PASI score (r = .260, p < .001) in psoriasis patients." (PMID 38578002, 2024). "Subgroup analyses discovered that pretreatment MALT1 had a stronger ability to predict PASI75 and 90 realizations in psoriasis patients receiving biologics (area under the curve [AUC]: 0.723 and 0.808) versus those without (AUC: 0.594 and 0.675)." (PMID 38578002, 2024). "Multivariate logistic regression analysis suggested that blood MALT1 was independently related to achieving PASI 75 (odds ratio = 1.362, p = .002) and PASI 90 (odds ratio = 1.629, p < .001) at M6 in psoriasis patients." (PMID 38578002, 2024). "Therefore, elevated blood MALT1 was related to achieving PASI 75 and 90 at M6 in psoriasis patients." (PMID 38578002, 2024). "In the collective, the MALT1/cJun/GLS1/glutaminolysis/H3 acetylation/T17 axis is involved in psoriasis pathogenesis and may represent a potential therapeutic target for psoriasis." (PMID 37443834, 2023). "In addition, blood MALT1 was also elevated in psoriasis patients who achieved PASI 90 at M6 versus those who did not achieve that (p < .001)." (PMID 38578002, 2024). "In fact, RNF7 abrogates ubiquitination of MALT1 induced by CARMA2shE138A expression, but not MALT1 ubiquitination induced by CARMA2shE142G expression, indicating that the various CARMA2 mutants associated with psoriasis so far identified can cause the disease through different molecular mechanisms." (PMID 29194363, 2017). "Interestingly, RNF7 abrogates ubiquitination of MALT1 and NEMO induced by the psoriasis-associated mutant CARMA2shE138A, but not that induced by the psoriasis-associated mutant CARMA2shE142G." (PMID 29194363, 2017). "Consequently, inhibiting MALT1 to block CARD14 signalling in psoriasis may also not be a viable option." (PMID 39145956, 2024).
gastric MALT lymphoma (13 papers, 2012 to 2025). "The findings of the current study reaffirm that excess MALT1 is associated with an elevated risk of disease progression or relapse in patients with gastric MALT lymphoma." (PMID 38418651, 2024). "In the second patient, FISH studies were negative for the 18q21 MALT1 gene, which has been associated with H. pylori-independent gastric MALT lymphoma." (PMID 32908756, 2020).